IL7 (interleukin 7)
Diseases named in the same sentence as IL7 in open-access papers (continued):
Sharing a sentence is not in itself a finding about the gene and the disease.
lymphopenia (continued). "Lymphopenia-induced proliferation of naïve CD8 T cells is driven by signals through both the TCR (engaging self peptide/MHC ligands) and the cytokines IL-7 and IL-15." (PMID 22879925, 2012). "Our results showed that in the presence of high IL-7 concentration the upregulation of CD95 on B cells leads to a higher sensitivity to CD95 mediated apoptosis, suggesting a potential link between lymphopenia and B cell apoptosis." (PMID 22194871, 2011). "The long-acting interleukin-7 NT-I7 is safe and increases absolute lymphocyte counts and CD4 T-cell counts in patients with newly diagnosed high-grade gliomas with severe treatment-related CD4 lymphopenia." (PMID 40703805, 2025). "At present moment, however, IL-7 or other cellular immunomodulators do not seem to be suitable for the amelioration of SIOD T cell lymphopenia." (PMID 39153074, 2024). "In allo-HCT, the lymphopenia created by the conditioning typically results in elevated plasma levels of γc cytokines (especially IL-7 and IL-15 46, 165), which are no longer consumed by resting T cells." (PMID 39543777, 2024). "Interleukin-7 is currently considered the most potent therapeutic candidate for the treatment of lymphopenia in cancer and non-cancer patients." (PMID 38481999, 2024). "Likewise, in cases of lymphopenia, the survival and maintenance of CD4+ memory T cells depend on IL-7 and the TCR pathway." (PMID 38675377, 2024). "Additionally, IL-7 not only leads to IL-7-dependent activation of STAT1 and STAT5 in the presence of lymphopenia, but also enhances T cell response to type-I IFN by regulating STAT1 protein expression level." (PMID 36142322, 2022). "A phase II clinical trial evaluating rhIL-7 in septic shock patients showed that IL-7 treatment restored T cell count in patients with severe lymphopenia in the absence of any severe side effects." (PMID 35246776, 2022). "Lymphopenia-induced proliferation favors expansion of CD8+ memory T cells, because CD8+ memory T cells express higher levels of a component of the IL-15 receptor (CD122) and CD4+ T cell homeostatic expansion is limited by IL-7-dependent STAT-1 activation." (PMID 33013907, 2020). "A recent phase II clinical trial evaluating IL-7 in patients with septic shock showed that IL-7 treatment restored T-cell count in patients with severe lymphopenia in the absence of any severe side effects." (PMID 30995946, 2019). "However, there is evidence that IL-7 serum concentrations are affected only at very low CD4+ T-cell numbers in AIDS patients, and these levels are far below lymphopenia described in tuberculosis." (PMID 28582466, 2017). "Thus, off-target inhibitory effects of IM on IL-7 and STAT5-p explain how T cell lymphopenia occurs in patients treated with IM." (PMID 28387753, 2017). "Furthermore, in different situations where lymphopenia takes place, such as neonatal thymectomy and HIV infection, IL-7 signaling is increased in order to reestablish basal T cell numbers." (PMID 26110906, 2015). "The increase of circulating IL-7 in ICL patients parallels that seen in HIV-infected patients with severely depleted CD4+ T cell counts, and likely reflects a compensatory mechanism that promotes homeostatic T cell proliferation in response to lymphopenia." (PMID 23383227, 2013). "IL-7 production is increased during HIV-induced lymphopenia, but this feedback is apparently not sufficient to maintain T cell homeostasis." (PMID 22958464, 2012). "Most importantly, there was no increase in serum IL-7 levels in RA, as compared with a fourfold rise in non-RA control individuals at the time of lymphopenia." (PMID 15642146, 2005). "By turning off IL7 transcripts and promoting myeloid cell egress, LTβR, in combination with TNFR and IL-1R signaling in MSCs, acts as a molecular switch between homeostatic hematopoiesis and a temporary state of lymphopenia that is required for emergency myelopoiesis to proceed." (PMID 36717247, 2023).
lymphopenia (continued). "As our results indicate that AD development in IL-7 KO NC mice is accompanied by a decreased number of CD4+ and CD8+ T cells, it would be worthwhile to investigate whether IL-7 is related to the onset of lymphopenia in AD patients." (PMID 37373104, 2023). "Conceivably, serum IL-7 concentration was also inversely related with the number of T cells, CD4+ and CD8+ cells; as a feedback response to the lymphopenia, which would further highlight the relation between lymphopenia and elevated IL-7 levels in SARS-CoV-2 infection." (PMID 34603318, 2021). "While maintenance immunosuppression is used to inhibit the proliferation of T cells following induction therapy, none of the therapies currently on the market target the IL-7 axis, despite its known role in the homeostatic expansion of T cells during lymphopenia." (PMID 29740426, 2018). "In human lymphopenia diseases, such as HIV infection, idiopathic CD4+ T lymphopenia, high dose chemotherapy and auto-immune diseases, patients often have increased circulating levels of IL-7 and a strong inverse correlation between the levels of IL-7 and the number of CD4+ T cells." (PMID 25955647, 2015). "The lymphopenia was neither triggered by caspase-dependent apoptosis nor macrophage-mediated clearance of T cells, nor diminished survival of naïve or recently activated T cells due to paucity of IL-7." (PMID 24466225, 2014). "By use of the acute lymphopenia models of sublethal irradiation and anti-CD4 depleting antibody treatment, we focused on systems which were shown to drive T cell proliferation by increased availability of IL-7, a setting which amplifies signals from weak TCR/self-pMHC contacts." (PMID 24115907, 2013). "This is probably due to the fact that nonmyeloablative patients experienced relatively mild lymphopenia (and thus continue to consume the IL-7 produced by stromal cells) as demonstrated by the persistence of median ALC counts of 110 cells/μL at the time of transplantation." (PMID 23437070, 2013). "The lymphopenia induced cytokine IL-7 may not act directly on peripheral B cells due to the lack of IL-7Rα expression on these cells." (PMID 22194871, 2011). "IL-7 is mainly produced by non-hematopoietic cells including keratinocytes in the skin, fibroblastic stromal cells in the bone marrow and is up-regulated to increase T-cell proliferation during lymphopenia in many diseases, such as HIV, hepatitis B virus and hepatitis C virus infections." (PMID 31138762, 2019). "In this model, the lymphopenia is not as severe as in RAG−/− mice and transferred cells compete with the host cells during reconstitution by undergoing slow homeostatic proliferation which is IL-7 dependent." (PMID 24603698, 2014). "Analysis of tumor-infiltrating lymphocytes (TILs) indicated that IL7-Fc injection did not increase the transfer of Thy1.1+CD8+ T cells, but increased the infiltration of endogenous Thy1.1−CD8+ T cells in immune-competent mice on day 13; this increase was impaired by inducing lymphopenia." (PMID 34440787, 2021).
Sepsis (120 papers, 2007 to 2026). Sepsis is defined as life-threatening organ dysfunction caused by a dysregulated host response to infection. "Endogenous IL-7 is closely associated with sepsis, whereas exogenous IL-7 shows promise for aiding the recovery of patients with sepsis, although further research is required." (PMID 41158471, 2025). "Collectively, dysregulated IL-7 is closely linked to sepsis pathology, immune compensation, and clinical outcomes." (PMID 41158471, 2025). "The PD-1 and interleukin 7 (IL-7) pathway has emerged as a significant mechanism inhibiting T cell function, thereby being linked to late sepsis and subsequent immunosuppression in individuals who survive the initial septic episode." (PMID 39064603, 2024). "The study emphasises the significance of monitoring IL-7 levels in patients with sepsis and septic shock; low levels were linked to a higher risk of mortality, as seen in the non-survivor group." (PMID 39684323, 2024). "Some clinical studies have also suggested that the IL-7/IL-7R signaling pathway is associated with improved lymphocyte function in sepsis patients." (PMID 39654893, 2024). "Sepsis-induced osteoblast ablation decreased the ability to secrete IL-7, thereby causing impaired lymphopoiesis." (PMID 36743311, 2023). "Recent murine and clinical studies have exploited the pro-survival features of IL-7 on T cells, as IL-7 treatment alleviates sepsis-indued T cell loss via preventing apoptosis and accelerating numerical recovery of lymphocytes." (PMID 36756117, 2023). "Recent studies have revealed that systemic inflammation, for instance, caused by sepsis, reduces the number of IL7-producing osteoblasts, which, in turn, diminishes the production of common lymphoid progenitors from HSCs24." (PMID 37773433, 2023). "In particular, PD-1 specific antibodies and recombinant IL-7 can reverse the basic immune deficiency of sepsis, improve the survival rate of a variety of clinically relevant septic animal models, and show good clinical tolerance." (PMID 36439140, 2022). "The onset of infection and subsequent occurrence of sepsis is linked with anomalous gene expression of γc cytokines IL-2 and IL-7." (PMID 21711552, 2011). "Our results indicate that the occurrence of infection and sepsis are linked with deficient γc family cytokines gene expression, specifically IL-2 and IL-7." (PMID 21711552, 2011). "Sepsis patients exhibit substantial alterations in IL-7, IL-7R, and associated factors." (PMID 41158471, 2025). "This study seeks to examine the dynamics of endogenous interleukin-7 (IL-7) and its associated regulatory factors in sepsis, and to elucidate the mechanisms by which exogenous IL-7 may confer therapeutic benefits." (PMID 41158471, 2025). "Among patients with sepsis, lower plasma levels of endogenous IL-7 may be associated with increased mortality over time." (PMID 41158471, 2025). "Survival in patients with sepsis may be associated with higher numbers of active lymphocytes and elevated IL-7 concentrations compared with healthy individuals." (PMID 41158471, 2025). "A study demonstrated that IL‐7 rejuvenated the delayed hypersensitivity reaction, reduced lymphocyte apoptosis caused by sepsis, counteracted the suppression of interferon γ (critical for macrophage activation) during sepsis, and enhanced survival in a mouse model of polymicrobial sepsis." (PMID 40453734, 2025). "Interestingly, we found that endogenous IL-7 levels differ between elderly sepsis survivors and elderly sepsis deaths, with higher endogenous IL-7 associated with higher mortality." (PMID 41158471, 2025). "Considering both aggravated immune cell apoptosis and profound immune exhaustion in elderly patients, with sepsis, IL-7 may be an underlying immunotherapeutic strategy, and its efficacy is highly anticipated." (PMID 38909272, 2024). "Additionally, IL-7 has gained the interest in recent times as it has been found to have both diagnostic and therapeutic potentials in sepsis cases." (PMID 35811678, 2022).
Sepsis (continued). "Dubbed as the “maestro of the immune system”, IL-7 is a pleiotropic cytokine with diverse biological properties, some of which may correct immunological abnormalities linked to sepsis." (PMID 26322041, 2015). "Patients with infection and sepsis have deficient IL-2 and IL-7 gene expression in PBLs." (PMID 21711552, 2011). "• The occurrence of infection and sepsis are linked with deficient IL-2 and IL-7 gene expression." (PMID 21711552, 2011). "Interleukin 7 and lipocalin 2-related interactions between bone metabolism and the immune system could partially explain the association of osteoporosis with an increased risk of infections and sepsis." (PMID 37384614, 2023). "The integration of IL-7 into sepsis management has the potential to transform outcomes for a condition that remains a leading cause of mortality in critically ill patients." (PMID 40005375, 2025). "Patients with severe sepsis exhibit higher IL-7 concentrations than those with uncomplicated sepsis, yet these levels remain lower than in healthy controls before treatment." (PMID 41158471, 2025). "The only correlations found between IL-7 levels and various lymphocyte subtypes were observed on day 1 in the sepsis group." (PMID 40005375, 2025). "Compared to healthy individuals, IL-7 in the plasma of sepsis patients slightly increase within 1–4 days." (PMID 41158471, 2025). "An important unresolved issue in sepsis immunology concerns the dynamics of endogenous IL-7 and the critical thresholds required to restore depleted and exhausted immune cells." (PMID 40005375, 2025). "In short, IL-7 therapies combat sepsis-induced lymphocyte apoptosis and metabolic dysfunction by modulating key survival and signaling pathways." (PMID 41158471, 2025). "Endogenous IL-7 levels appear inadequate to overcome the immunosuppressive environment induced by sepsis." (PMID 40005375, 2025). "We included 10 studies investigating the potential therapeutic mechanisms of exogenous IL-7 in sepsis." (PMID 41158471, 2025). "In clinical trials, cytokines (INF-gamma or GM-CSF or IL7) are being tested as immune modulating therapeutics in sepsis to improve patient’s immune function." (PMID 41229429, 2025). "This study builds on a 2021 systematic review that detailed the functions of IL-7 in sepsis and identified key molecular changes." (PMID 41158471, 2025). "Endogenous IL-7 levels appear inadequate to overcome the immunosuppressive environment induced by sepsis, underscoring the rationale for exploring the exogenous administration of this lymphocyte growth factor in the clinical management of sepsis." (PMID 40005375, 2025). "A comprehensive and systematic evaluation plan that integrates IL-7 with other relevant markers is valuable for advancing our idea and clinical management of sepsis." (PMID 41158471, 2025). "In sepsis survivors, IL-7 levels can rise and remain comparable to those of healthy individuals for up to one year." (PMID 41158471, 2025). "Employing endogenous IL-7 and IL-7R as prognostic markers in sepsis currently lacks a well-defined standard." (PMID 41158471, 2025). "Several research groups have studied IL-7 in animal models of sepsis and demonstrated its ability to prevent lymphocyte apoptosis by restoring the functionality of CD4+ and CD8+ T cells, thus improving survival." (PMID 40005375, 2025). "The primary mechanisms of IL-7 in vitro for sepsis animal and human blood include immune system recovery, inflammation regulation, and anti-apoptosis." (PMID 41158471, 2025). "In HIV patients, these cells can be reduced and restored by IL-7, whereas in sepsis patients, their levels tend to remain elevated." (PMID 41158471, 2025). "Further research is needed to elucidate the complex interactions between IL-7 and other immune components, as well as its role in modulating inflammation and promoting immune recovery in sepsis." (PMID 41158471, 2025).
Sepsis (continued). "Regarding the dosing of rhIL-7, it would be rational to administer it at a concentration sufficient to elevate IL-7 levels above the median observed in sepsis survivors." (PMID 41158471, 2025). "In sepsis, blood levels of endogenous IL-7 are typically elevated initially as a result of immune cell activation and endothelial damage caused by the infection." (PMID 41158471, 2025). "Some studies have trialed immunostimulatory therapies, such as anti-IL-7 and anti-PD-1 antibodies, in patients with sepsis to counter immunosuppression, with mixed results." (PMID 39967662, 2025). "Sepsis patients often have compromised immune function, and several studies have shown that IL-7 can regulate immune by enhancing T cell activity." (PMID 41158471, 2025). "This suggests that, although patients with sepsis have impaired IL-7 function, they are still capable of secreting higher amounts of IL-7, likely as a result of epithelial and endothelial cell activation." (PMID 41158471, 2025). "The standard receiver operating characteristic (ROC) curve analysis of IL-7 was employed to evaluate its diagnostic accuracy and to establish the optimal cut-off value for IL-7 levels, distinguishing patients with sepsis or septic shock from the control group." (PMID 40005375, 2025). "IL-7 therapies, which promote the survival and function of T-cells, have shown promise in reversing lymphopenia and enhancing immune recovery in sepsis patients." (PMID 39594987, 2024). "For example, the administration of IL-7 has been observed to inhibit the process of lymphocyte apoptotic cell death that is induced by sepsis." (PMID 38510969, 2024). "In contrast, the interventions involving IL-7 largely target the later stages of sepsis, which are marked by immunosuppression." (PMID 38601150, 2024). "Analysing the sepsis/septic shock groups, on day 1 of study inclusion, with the healthy control group, we found the cutoff value of IL-7 to be 1.94 pg/mL with an AUC of 0.8547 (p < 0.0001)." (PMID 39684323, 2024). "IL-7 and IL-15 have been identified as prognostic biomarkers of sepsis and septic shock and are strongly correlated with inflammatory markers and mortality, particularly IL-7." (PMID 38716051, 2024). "Recent literature regarding the IL-7 cutoff value is scarce, especially concerning sepsis and septic shock." (PMID 39684323, 2024). "Further investigation is warranted to explore the synergistic potential of Flt3 therapy with other established therapeutics, such as IL-7, in the management of sepsis." (PMID 39720718, 2024). "IL-7 facilitates communication between Th1 and Th17 lymphocytes in sepsis, resulting in enhanced neutrophil recruitment and bacterial clearance without increasing early tissue injury." (PMID 38510969, 2024). "The ability of IL-7 to promote T cell viability, trafficking, and functionality aligns with observed improvements in survival rates among sepsis patients." (PMID 38601150, 2024). "In a phase II trial, IL-7 administration in sepsis survivors increased the numbers of circulating CD4+ and CD8+ T-cells, improving the patients’ ability to mount an immune response to secondary infections." (PMID 39594987, 2024). "According to the ROC curve of IL-7 analysis, the cutoff value for IL-7 was 1.94 pg/mL, with a sensitivity of 74.23% and a specificity of 75.34% for sepsis/septic shock, and the area under the curve (AUC) was 0.8547 (p < 0.0001), 95% CI 0.79–0.90." (PMID 39684323, 2024). "Research has found that of IL-7 levels diminish in individuals with sepsis, resulting in a reduction in T lymphocyte count, with the degree of decline correlating with the severity of sepsis." (PMID 39252831, 2024). "IL-7, a cytokine, exhibits a plethora of supplementary actions that manifest considerable advantageous effects in sepsis, and it has the capacity to counteract a significant pathological aberration observed in sepsis." (PMID 38510969, 2024).